IL33 (interleukin 33)
Diseases named in the same sentence as IL33 in open-access papers (continued):
Sharing a sentence is not in itself a finding about the gene and the disease.
pneumonia (13 papers, 2014 to 2025). An acute, acute and chronic, or chronic inflammation focally or diffusely affecting the lung parenchyma, caused by an infection in one or both of the lungs (by bacteria, viruses, fungi, or mycoplasma.). "Secretome analysis of A549 cells infected with Mycoplasma pneumoniae revealed higher levels of IL-33 mimicking in vivo conditions whereby higher than normal IL-33 levels are evident in plasma and bronchoalveolar lavage fluid from patients with M. pneumonia-associated pneumonia." (PMID 32161586, 2020). "In a mouse model, after induction of pneumonia with Staphylococcus aureus, an IL-33-induced increase in eosinophil levels inhibited acute lung injury as indicated by reduced pulmonary edema and higher oxygen saturations." (PMID 38972349, 2024). "It has been shown that IL-33 induction of type 2 responses is protective in lethal models of S. aureus sepsis and pneumonia by counterbalancing proinflammatory responses." (PMID 36040164, 2022). "IL-33 can be protective during pneumonia-induced acute lung injury, whereas it contributes to early inflammation-associated lung injury during abdominal sepsis." (PMID 36570798, 2022). "Very low levels of IL-33 were seen in 2 patients with severe pneumonia, 2 patients who succumbed to their illness and 2 patients with prolonged shedding." (PMID 33199778, 2020). "The results showed that the alveolar volume expanded, the alveolar septum thickened, and the severity of pneumonia increased in BPD mice treated with IL-33." (PMID 33178840, 2020). "In the current study, IL-33 and IL-13 were found to be significantly elevated in the pneumonia model." (PMID 24956279, 2014). "The finding of elevated IL-33 levels indicated that IL-33 might play a role in the recruitment of immune cells to the lung and may promote bacterial clearance in the pneumonia model." (PMID 24956279, 2014). "Further sample collection, including plasma, pleural effusion, and BALF, is necessary to evaluate the predictive value of IL-18, the IL-18/IL-38 ratio, and IL-33 for PPE and to determine whether respiratory colonization by Hi can attenuate inflammatory cytokine production during pneumonia." (PMID 40352606, 2025).
renal fibrosis (13 papers, 2018 to 2025). A final common manifestation of a wide variety of chronic kidney diseases characterized by glomerulosclerosis and tubulointerstitial fibrosis. "Our previous study reported that the deficiency of IL33 or IL1RL1 partially reversed the UUO-induced renal fibrosis." (PMID 32102434, 2020). "In a model of cardiorenal syndrome following AKI, blockade of IL-33 markedly attenuated myocardial hypertrophy and renal fibrosis, highlighting the therapeutic potential of targeting inter-organ communication pathways." (PMID 40521043, 2025). "The proliferation of ILC2s induced by IL‐33 suppressed the transition of renal fibroblasts to myofibroblasts, thereby ameliorating renal fibrosis." (PMID 40801800, 2025). "There is evidence to indicate that IL-33, a proinflammatory cytokine that mediates tissue inflammation, contributes to CKD and is also implicated in AKI, as well as in the progression of renal fibrosis." (PMID 38590952, 2024). "High-dose administration of IL-33 promoted renal fibrosis via AKI, but the inhibition of IL-33 was decreased AKI-induced renal fibrosis." (PMID 34381446, 2021). "In this review, we have focused on discussing the role of the IL-33/ST2 pathway in the development and progression of renal fibrosis as well as the underlying mechanisms of this process." (PMID 35046838, 2021). "In particular, in vivo studies in IL-33-deficient transgenic mice further supported the importance of the IL-33/ST2 pathway in the progression of renal fibrosis." (PMID 35046838, 2021). "Recent studies have shown that a sustained activation of IL-33/ST2 pathway promotes the development of renal fibrosis." (PMID 35046838, 2021). "We hope this review will contribute to the comprehensive studies of the IL-33/ST2 pathway in renal fibrosis and help in the development of novel therapeutic agents." (PMID 35046838, 2021). "In fact, this review discusses the current progress in research related to the IL-33/ST2 pathway in renal fibrosis to provide new insights into developing treatment options for CKD patients." (PMID 35046838, 2021). "Generally, the mechanisms of the IL-33/ST2 pathway in the progression of renal fibrosis can be summarized in two aspects." (PMID 35046838, 2021). "Here, we review the mechanisms and potential applications of the IL-33/ST2 pathway in renal fibrosis; such that it can help clinicians and researchers to explore effective treatment options and develop novel medicines for CKD patients." (PMID 35046838, 2021). "The number of ILC2s decreased in unilateral ureteral obstruction (UUO) mice kidneys, and IL‐33 pretreated before UUO could protect renal fibrosis." (PMID 40801800, 2025). "Previous studies showed that blocking IL-18 and IL-33 ameliorated renal fibrosis." (PMID 40131554, 2025). "Previous studies have shown that blocking IL-18 and IL-33 can improve renal fibrosis." (PMID 38152332, 2023). "Meanwhile, the IL-33/ST2 pathway appears to be a promising therapeutic target for renal fibrosis." (PMID 35046838, 2021). "IL-33 promotes renal fibrosis through macrophages and increases secretion of IL-13 and TGF-β1." (PMID 35046838, 2021). "Short-term exogenous IL-33 treatment at the early stage of disease onset could be beneficial, whereas long-term (high-dose) treatment may exacerbate the progression of renal fibrosis." (PMID 32102434, 2020). "In addition to the renal protective functions in AKI models, recent studies have reported the detrimental effects of IL-33, which involve promoting renal fibrosis." (PMID 32102434, 2020). "Hence, IL-33 signaling in ILC2s plays a critical role in the pathogenesis of IRI–induced renal fibrosis and treatment with IL-33 inhibitor reduced pro-inflammatory cytokine and chemokine levels in the kidneys of mice following IRI insult." (PMID 30405626, 2018). "Intriguingly, pretreatment with IL-33 before unilateral ureteral obstruction (UUO) has been reported to expand renal ILC2s and Tregs and to ameliorate renal fibrosis." (PMID 40521043, 2025).
renal fibrosis (continued). "To determine the effect of MAFF on renal fibrosis and inflammation, we first detected MAFF expression after IL-33 treatment." (PMID 39412062, 2024). "The commonly used method to study renal fibrosis is unilateral ureter obstruction (UUO)-model, and IL-33 increased in serum and urine in this model." (PMID 34381446, 2021). "Our previous study demonstrated that ILC2s induced by exogeneous recombinant IL-33 have preventative but not therapeutic effects on renal fibrosis in a mouse UUO model." (PMID 36725898, 2023).
Acute hepatitis (12 papers, 2012 to 2022). Acute hepatic injury resulting from inflammation typically accompanied by increased serum alanine transaminase activity. "We observed the protective effect of IL-33 in this acute hepatitis model demonstrated by increased liver injury, weight loss, and the earlier death of the IL-33 KO mice." (PMID 28607531, 2017). "Similarly, IL-33 contributes significantly in the pathogenic course of acute hepatitis activated by the plant lectin concanavalin A (ConA)." (PMID 35056005, 2022). "The present study investigated the role of IL-33 in the natural model of acute hepatitis in mice induced by specific mouse hepatitis coronavirus (MHV3)." (PMID 28607531, 2017). "Our results substantially differ from those that describe the activity of IL-33 in models of acute hepatitis." (PMID 28611297, 2017). "Here, we studied the effect of depletion of NK cells by anti-ASGM1 antibody on D-GalN Poly(I:C) induced acute hepatitis and expression of IL-33." (PMID 24058536, 2013). "We investigated the expression and cellular sources of IL-33 in L2-MHV3 induced acute hepatitis in C57BL/6 mice." (PMID 24058536, 2013). "Here, we add TLR3 mediated expression of IL-33 in liver sinusoidal endothelial cells, vascular endothelial cells and hepatocytes in acute hepatitis in mice in a pathophysiological context." (PMID 24058536, 2013). "Meanwhile, IL-33 expression in hepatocytes was also blocked during Con A-induced acute hepatitis in tumour necrosis factor-related apoptosis-inducing ligand- (TRAIL-) deficient mice, and IL-33-deficient mice exhibited more severe Con A-induced liver injury than WT mice." (PMID 29180837, 2017). "Thus, IL-33 affected or controlled the recruitment of neutrophils in the liver following L2-MHV3 acute hepatitis." (PMID 28607531, 2017). "However, in the setting of ConA-induced acute hepatitis, IL-33 exerts a dual activity through its cellular targets." (PMID 28611297, 2017). "While the cellular source of IL-33 in viral liver pathology is poorly known in a mouse model, we first aimed to investigate the expression and cellular sources of IL-33 in a Poly(I:C)-induced acute hepatitis." (PMID 24058536, 2013). "Since repeated application of IL-33 enhances regulatory Tregs that are known regulators of liver inflammation, these cells are suggested to confer IL-33-mediated protection against acute hepatitis by limiting the function of pro-inflammatory cells, including ILC2s." (PMID 30999584, 2019). "IL-33/ST2 axis is involved in the pathogenesis of liver injuries, such as viral hepatitis, acute hepatitis, and fatty liver disease." (PMID 34674752, 2021). "We found increased expression of IL-33 in liver following Poly(I:C) and L2-MHV3 induced acute hepatitis in mice." (PMID 24058536, 2013). "Similarly, the transcript level of antiviral IFN-beta (IFN-β) increased exponentially following L2-MHV3-induced acute hepatitis (48 h and 72 h PI) compared to PBS control with a comparable expression in WT and IL-33 KO mice." (PMID 28607531, 2017). "Lack of IL-33/ST2 signaling enhances acute hepatitis and EAE." (PMID 30498495, 2018).
acute myeloid leukemia (12 papers, 2016 to 2025). Acute myeloid leukemia (AML) is a group of neoplasms arising from precursor cells committed to the myeloid cell-line differentiation. "We have previously reported elevated IL-33 levels in patients with acute myeloid leukaemia (AML) at diagnosis along with upregulated expression of its receptor, interleukin-1 receptor-like 1 (IL1RL1), as compared to the healthy controls." (PMID 34435521, 2021). "In addition, the combination of IL-33 blockers with programmed death-1 monoclonal antibodies could successfully inhibit acute myeloid leukaemia, and its combination with imatinib could also prevent chronic myeloid leukaemia resistance." (PMID 33308251, 2020). "In acute myeloid leukemia (AML)-bearing mice, IL-33 also increases CD8+ T cell proliferation and activation, and reverses DC tolerance." (PMID 33261061, 2020). "Studies performed in animal models have showed that IL-33 augments effector T cell responses in LCMV infection, GVHD, and murine acute myeloid leukemia." (PMID 30564243, 2018). "In terms of hematological malignancies, the effects of IL-33 are controversial as a negative role has been identified for Chronic myelogenous leukemia (CML), while a positive role was shown for Acute myeloid leukemia (AML)." (PMID 32363166, 2020). "Another new function of IL-33 discovered from non-basophilic leukemia, a rare subtype of acute myeloblastic leukemia, indicated IL-33 enhanced the basophilic differentiation of MYB-GATA1 expression, demonstrating a new role of IL-33 in leukemic cells and CD34-positive primary cells." (PMID 30619376, 2018).
amyloid (12 papers, 2019 to 2026). "Our data highlight the pharmacological potential of the IL-33/ST2 axis in counteracting amyloid-related pathologies." (PMID 41751358, 2026). "For instance, previous research has shown that IL-33 in the brain reduces soluble Aβ levels and amyloid plaque deposition in a mouse model of AD." (PMID 40764944, 2025). "In fact, IL-33 has proposed to hold anti-inflammatory and protective functions in AD and IL-10, which can be also induced by IL-33 itself, exerts anti-inflammatory actions and was suggested to negatively regulate amyloid pathology in AD-like conditions." (PMID 35515001, 2022). "An animal study showed that peripheral IL-33 administration reduced soluble Aβ levels and amyloid plaque deposition and reversed synaptic plasticity impairment and cognitive decline in AD mouse models." (PMID 32678011, 2020). "IL-33 and IL-1β belong to the IL-1 family, and IL-1β has been shown to reduce amyloid plaque pathology in AD mouse models." (PMID 32678011, 2020). "IL-33 administration could promote the polarization of microglia toward the anti-inflammatory type and decrease soluble β-amyloid levels and amyloid plaque deposition in AD mice." (PMID 36138980, 2022). "To assess whether the increased amyloid plaque burden resulted in an exacerbation of pro-inflammatory responses, we measured levels of the inflammation-associated molecules CXCL1, CCL3, IL-33, TNFα, IL-6, and IL-1β by multiplexed MSD ELISA." (PMID 32943069, 2020). "We observed that FAP 0 patients already exhibited a significant increase in levels of IL-33, IL-1β and IL-10, suggesting that the alterations in immune response might occur before amyloid deposition and symptom appearance." (PMID 31253122, 2019). "IL-33 administration into APP/PS1 mice has been shown to reduce soluble Aβ levels and amyloid plaque deposition by promoting the recruitment of microglia for enhancing Aβ phagocytic activity." (PMID 39548583, 2024). "IL-33 treatment in D-gal–administered mice significantly downregulated BACE1 protein levels in cortex and hippocampus regions, when compared with chronic D-gal–administered mice, suggesting that IL-33 has an inhibitory effect on the progression of amyloid pathology in D-gal–induced aged mice." (PMID 39224568, 2024). "IL-33 can reverse the synaptic plasticity damage and memory deficits in APP/PS1 mice, and its mechanism may be to promote the differentiation of microglia into an anti-inflammatory phenotype and reduce soluble Aβ levels and amyloid plaque deposition." (PMID 33854693, 2021).
emphysema (12 papers, 2019 to 2025). "The results of the present study suggest that AIM is also partially associated with IL-33-induced upregulation of type-2 inflammation, which leads to emphysema in the PPE model." (PMID 37592330, 2023). "The results of these histological analyses suggested that IL-33−/− mice have increased susceptibility to elastase-induced emphysema compared to WT controls." (PMID 33992109, 2021). "These histological observations indicated that IL-33−/− mice are more susceptible to CSE-induced emphysema than WT mice." (PMID 33992109, 2021). "ILC2‐deficient mice were protected from CS‐induced emphysema, but had increased collagen deposition, and IL‐33 and IL‐13 expression." (PMID 30260499, 2019). "However, a recent study reported that a complete loss of IL-33 enhances emphysema formation in both PPE- and CSE-induced models." (PMID 37592330, 2023). "However, IL-33-deficiency enhances murine emphysema caused by intratracheal administrations of elastase or cigarette smoke extract." (PMID 35493481, 2022). "Our data suggested that although IL-33 may affect CS-induced airway inflammation, complete loss of IL-33 may enhance emphysema and potentially be harmful in patients with COPD." (PMID 33992109, 2021). "We demonstrated that the loss of IL-33 may enhance the development of emphysema." (PMID 33992109, 2021). "We assessed lung function to clarify the role of IL-33 in the development of elastase-induced emphysema." (PMID 33992109, 2021). "Instead, the level of HGF, which protects against the development of emphysema, was significantly lower in IL-33−/− mice compared to WT mice following PPE instillation." (PMID 33992109, 2021). "We determined the role of interleukin (IL)-33 in the development of emphysema using porcine pancreas elastase (PPE) and cigarette smoke extract (CSE) in mice." (PMID 33992109, 2021). "The present study was performed to investigate the susceptibility of IL-33-deficient (IL-33−/−) mice to porcine pancreas elastase (PPE) and CSE, to clarify the role of IL-33 in the pathogenesis of emphysema." (PMID 33992109, 2021). "CS‐exposed Rorafl/flIl7rCre mice were protected from emphysema, but had increased IL‐33/IL‐13 expression and collagen deposition compared to WT CS‐exposed mice." (PMID 30260499, 2019). "The bronchoalveolar lavage (BAL) interleukin 13 (IL‐13), IL‐4, and IL‐5 levels in the overlap model were higher than in the pulmonary emphysema model and lower than in the type 2 airway inflammation model, but IL‐33 level in the lung was higher than in other models." (PMID 38652015, 2024). "We next hypothesized that the emphysema model would release more IL‐33 in the alveoli after Alternaria alternata inhalation." (PMID 38652015, 2024). "We further assessed whether the emphysematous changes in IL-33−/− mice were enhanced in the CSE-induced emphysema model." (PMID 33992109, 2021). "As loss of IL-33 enhances emphysematous changes, we examined whether IL-33 had a protective effect on PPE-induced emphysema in WT mice." (PMID 33992109, 2021). "Senescent cells secrete SASP mediators, such as MMP-12, TGFβ1, and IL-33, affecting the extracellular matrix homeostasis, which in combination with the loss of regenerative capacity of senescent AECII progenitors, leads to alveolar destruction and emphysema." (PMID 31428695, 2019). "However, the role of IL-33 in the development of emphysema remains controversial." (PMID 37592330, 2023). "Although complete loss of IL-33 may enhance the development of emphysema, partial blockade of IL-33 does not appear to promote emphysematous changes in the lung." (PMID 33992109, 2021). "Our results demonstrated that airspace enlargement of the lung was significantly enhanced in IL-33−/− mice compared to WT mice, in both PPE and CSE-induced emphysema models." (PMID 33992109, 2021).
emphysema (continued). "Biologics targeting upstream alarmins (e.g., IL-33/TSLP) and downstream cytokines (e.g., IL-1β, IL-6) aim to disrupt inflammatory redundancy; cell-based and regenerative approaches represent long-term precision strategies for emphysema." (PMID 41024111, 2025). "Treatment with anti-ST2 receptor antibody did not enhance emphysema development, suggesting that partial IL-33 blockade is not sufficient to induce emphysema." (PMID 33992109, 2021). "We have shown that a congenital IL-33 defect might enhance elastase- and CSE-induced emphysema." (PMID 33992109, 2021). "Second, treatment with IL-33 did not significantly suppress emphysema development." (PMID 33992109, 2021). "In addition, AT2 cells represent a significant source of IL-33, and a lack of Gq/11 signaling promotes IL-33-mediated alveolar macrophage activation and emphysema." (PMID 30654796, 2019). "In the present study, however, VEGF levels in the lungs were not different between IL-33−/− and WT mice following instillation of PPE or CS; therefore, VEGF may not have been affected in our emphysema models." (PMID 33992109, 2021).